SPATA17 (spermatogenesis associated 17)
Synonyms: IQCH; MOT17; FAP305; CFAP305; MSRG-11; MSRG11
Tractability: PROTAC: ubiquitination databases record sites on it.
Gene: Protein-coding gene on chromosome 1 (217,631,324 to 217,871,696, forward strand). Ensembl gene ENSG00000162814.
Subcellular location: Cytoplasm
Subcellular location (Human Protein Atlas): Cytosol; Nucleoli; Nucleoplasm
Gene Ontology:
Molecular function: protein binding
Cellular component: cytoplasm
Genetic constraint (gnomAD): Loss-of-function variants: 36 observed, 36.01 expected, observed/expected ratio (o/e) 1, 90% interval 0.76 to 1.32. The upper end of that interval is the gene's LOEUF score, 1.32, which puts it in group 5 of 6, group 1 being the genes least tolerant of losing a copy. Missense variants: 303 observed, 290.37 expected, observed/expected ratio (o/e) 1.04, 90% interval 0.95 to 1.15. Synonymous variants: 97 observed, 102.41 expected, observed/expected ratio (o/e) 0.95, 90% interval 0.8 to 1.12.
Homologues: Orthologues: chimpanzee SPATA17 (99% identical), macaque SPATA17 (98% identical), rabbit SPATA17 (84% identical), dog SPATA17 (84% identical), pig SPATA17 (79% identical), mouse Spata17 (76% identical), rat Spata17 (76% identical), guinea pig SPATA17 (73% identical), tropical clawed frog SPATA17 (52% identical), zebrafish spata17 (48% identical), Drosophila melanogaster CG18063 (17% identical), Drosophila melanogaster CG31735 (17% identical), and 2 more.
Diseases named in the same sentence as SPATA17 in open-access papers:
SPATA17 is named in the same sentence as 2 diseases in open-access papers, as found by Europe PMC text mining. Sharing a sentence is not in itself a finding about the gene and the disease. The quoted sentences say what the papers report.
anorexia nervosa (1 paper, 2023). A disorder most often seen in adolescent females characterized by a refusal to maintain a minimally normal body weight, an intense fear of gaining weight, a disturbance in body image, and, in postmenarcheal females, the development of amenorrhea. "In previous studies, the SPATA17 gene has been linked to germ cell apoptosis in transgenic mice, anorexia nervosa and to degenerative diseases." (PMID 36834337, 2023).
SPATA17 also shares sentences with these, for which no sentence is quoted: degenerative diseases (1 paper).